MMP24 (matrix metallopeptidase 24)
Diseases named in the same sentence as MMP24 in open-access papers (continued):
Sharing a sentence is not in itself a finding about the gene and the disease.
head and neck cancer (1 paper, 2020). A primary or metastatic malignant neoplasm affecting the head and neck. "Expression levels of MMP10, MMP19, MMP24, and MMP25, which were associated with prognosis in head and neck cancer, were identified using Kaplan–Meier method and log-rank test." (PMID 32850314, 2020). "Expression levels of MMP10, MMP19, MMP24, and MMP25 were associated with prognosis in TCGA cohort of head and neck cancer by Kaplan-Meier analysis." (PMID 32850314, 2020).
keloid (1 paper, 2007). An irregularly shaped, elevated mark on the skin caused by deposits of excessive amounts of collagen during wound healing. "A number of MMPs were equally expressed in leiomyomas, keloids and peritoneal adhesions with the exception of lower MMP-14, MMP-24 and MMP-28 expression in leiomyomas, suggesting that these tissues are potential target of their proteolytic actions." (PMID 17718906, 2007).
kidney failure (1 paper, 2023). An acute or chronic condition that is characterized by the inability of the kidneys to adequately filter the blood. "MMP24 expression was localized to epithelial cells from distal and proximal tubules, collecting duct and Henle’s loop; and tubular epithelial cells expressing MMP24 were associated with tubular atrophy, a marked contributing factor for DN development and kidney failure." (PMID 37445827, 2023).
Parkinson disease (1 paper, 2019). A progressive degenerative disorder of the central nervous system characterized by loss of dopamine producing neurons in the substantia nigra and the presence of Lewy bodies in the substantia nigra and locus coeruleus. "The DAVID database also shows an association of the MMP24 gene with Parkinson’s disease." (PMID 31784692, 2019).
tumor (13 papers, 2018 to 2024). "The mRNA genes of mitogen activated protein kinase kinase kinase 6 (MAP3K6)/membrane matrix metalloproteinase 24 (MMP24) signal molecules, which are closely related to tumor proliferation and migration, were significantly down-regulated." (PMID 38436092, 2024). "We then explored the relationship between REST and MMP24 in addition to the association of REST expression with patient and tumor characteristics." (PMID 39273639, 2024). "In our study, abnormal hypermethylation of promoter CpG dinucleotides of the MMP2, MMP23B, MMP24, MMP25, and MMP28 was associated with HER2-positive tumor status, and, to a different extent, with CpG island hypermethylated epigenomic BC subtype." (PMID 32397602, 2020). "It remains unclear why the role of MMP24 in tumor aggressiveness is opposite to that of MMP7 and their roles are cancer type-dependent." (PMID 32093160, 2020). "Indeed, Fisher’s exact test supports a statistically significant association of abnormal methylation of MMP24 and MMP25 promoters in tumor samples with their attribution to the hypermethylated BC subtype with p = 0.033 for MMP24 and p = 0.002 for MMP25." (PMID 32397602, 2020). "Thus, MMP24 may negatively regulate the aggressiveness of cancer cells under the stiff ECM environment during tumor progression." (PMID 32093160, 2020). "We proceeded to examine whether expression of MMP24 affects tumor aggressiveness." (PMID 32093160, 2020). "Significant changes have been detected in the tumor microenvironment pathway including genes MMP19, MMP24, and CSF2, as well as PLAU, BCL2, TIAM1 and Rac1." (PMID 38003292, 2023). "AHCY-deficient SW480 cells exhibit significant upregulation of genes important for the tumor microenvironment pathway, such as MMP19, MMP24, and CSF2, as well as upregulated activation of PLAU and BCL2." (PMID 38003292, 2023). "We next examined the relationship between MMP24 and MMP7 expression with respect to tumor aggressiveness." (PMID 32093160, 2020). "In the present study, we demonstrated that SNCG, as a secreted protein, also controlled secretion of many proteins in the tumor microenvironment, including ECM proteins such as fibronectin, vitronectin, the MMPs like MMP-2 and MMP-24." (PMID 29903032, 2018). "In the present study, increased MMP-24 shed and MMP-2 activation was observed in SNCG-treated tumor cells, suggesting that SNCG was an upstream regulator of MMP-24 and MMP-2." (PMID 29903032, 2018). "Although MMPs contribute to ECM breakdown and tumor progression, elevated MMP24 levels were not seen in the human cancer tissue." (PMID 39273639, 2024). "The different roles of MMP24 and MMP7 in cancer progression could be due to the different ECM types surrounding the tumor, which control angiogenesis for metastasis and growth of cancer cells." (PMID 32093160, 2020). "We also discovered that ECM substrates of MMP24 and MMP7 are different and that MMP7 expression promotes angiogenesis, which has a central role in tumor growth and metastasis, whereas the role of MMP24 in angiogenesis has not been clarified." (PMID 32093160, 2020). "We could see that about half MMPs are highly expressed in tumor tissues as compared with normal tissues, including MMP9, MMP10, MMP11, MMP12, MMP15, MMP25, MMP26 (all, P<0.05), while some other MMPs decreased in tumor tissues, including MMP2, MMP14, MMP16, MMP24, MMP28(all, P<0.05)." (PMID 32669958, 2020).
cancer (11 papers, 2018 to 2025). A tumor composed of atypical neoplastic, often pleomorphic cells that invade other tissues. "Further studies are required for better understanding of the mechanism underlying cancer progression that involves the link between MMP24 and MMP7." (PMID 32093160, 2020). "In these types of cancers, cancer aggressiveness would be promoted when expression of MMP24 induced by YAP-TEAD is hampered." (PMID 32093160, 2020). "Considering that cancer cell behaviors such as invasion and proliferation are often promoted in response to rigid substrates, MMP24 is likely to act as a negative regulator for cancer progression." (PMID 32093160, 2020). "The results showed that salidroside could significantly up-regulate the expression of miR-1343-3p, and significantly down-regulate the expression of MAP3K6 and MMP24 genes in cancer cells." (PMID 38436092, 2024). "Beyond EMT, evaluation of AHR-regulated expression and activity patterns revealed several targets implicated in cancer progression, including members of the matrix metalloprotease family (MMPs, MMP9 and MMP24), asparagine synthetase (ASNS) and the ATF4 transcription factor." (PMID 33214553, 2020). "Specific reports for HNSCC may not be available for all the genes of interest but published studies clearly document the cancer involvement for MMP24, EIF6 FAM83C and GDF5." (PMID 29371888, 2018). "Thus, MMP24 would be a prognostic factor in cancer patients and therefore, controlling MMP24 expression could be a viable treatment strategy to block cancer progression." (PMID 32093160, 2020). "Thus, MMP7 could have a role opposite to that of MMP24 in the regulation of aggressiveness of cancer cells." (PMID 32093160, 2020). "We here demonstrate that, though hypermethylation of certain CpGs in promoter regions of the MMP2, MMP23B, MMP24, MMP25, and MMP28 genes is cancer specific, it lacks independent biological or clinical value, being rather a function from HER2 activation." (PMID 32397602, 2020). "Seven MMPs (MMP7, MMP11, MMP12, MMP13, MMP24, MMP27, and MMP28) had an AUC of greater than 0.95 for at least one cancer type." (PMID 31200666, 2019). "While the exact role of MMP24 in cancer is not clear, many studies show high expression is associated with poor outcomes." (PMID 35177031, 2022). "Although the inhibition of the T-box transcription factor Brachyury is shown to downregulate MMP2 and MMP24 in cancer, to date, there are no reports on the direct participation of TBX4 in MMP gene expression." (PMID 31311130, 2019). "This may be due to a more prominent role for MMP24 during the early pathogenesis of EC, but not after it has already developed, as individual MMPs are involved in varying degrees in the different stages of cancer progression by activating other MMPs or degrading ECM components." (PMID 39273639, 2024). "There was decreased MMP24 expression in the cytoplasm compared to the nuclear REST expression in the glands of control specimens (p < 0.05), but not in the cancer specimens." (PMID 39273639, 2024).
psychiatric diseases (1 paper, 2022). "Our results showed that MMP genes such as MMP-15, MMP-16, MMP-17, MMP-24 and MMP-28 were expressed highly or moderately in brain, implying the values in investigation of more genes in association with psychiatric diseases." (PMID 35444067, 2022).
MMP24 also shares sentences with these, for which no sentence is quoted: pancreatic cancer (2 papers); adenomyosis (1); adrenocortical tumors (1); amyloidosis (1); astrocytomas (1); bladder cancer (1); brain cancer (1); brain tumors (1); breast tumours (1); diabetes (1); ependymoma (1); gastric tumors (1); glioblastoma (1); hepatocellular carcinoma (1); leiomyoma (1); lung adenocarcinoma (1); malignant glioma (1); meningioma (1); neuropathic pain (1); prostate carcinoma (1); pulmonary fibrosis (1); renal carcinoma (1); retinopathy (1); Sepsis (1); Stroke (1); uveal melanoma (1); viral hepatitis (1).